SIRT1 (sirtuin 1)
Diseases named in the same sentence as SIRT1 in open-access papers (continued):
Sharing a sentence is not in itself a finding about the gene and the disease.
tumor (continued). "Elevated SIRT1 tissue levels, in fact, have been found to increase in NMSC, suggesting a potential tumor-promoting function." (PMID 39766219, 2024). "Sirtuins, such as SIRT1, SIRT2, and SIRT6, interact with crucial signaling pathways, influencing tumor metabolism, genomic stability, and the progression of ADM." (PMID 39682281, 2024). "SIRT1, interacting with CLOCK-BMAL1, regulates PER2 and exosome secretion, impacting the tumor microenvironment and progression in breast and ovarian cancer, and is crucial in tumor dynamics and metastasis." (PMID 39061191, 2024). "SIRT1 deacetylates the acetyl of H3K4, H3K9 and H4K16 to regulate the transcription of tumor-related genes." (PMID 37583461, 2023). "SIRT1 plays pivotal roles in metabolic reprogramming between glycolysis and FAO and is, therefore, a potential therapeutic target restricting tumor growth." (PMID 37063423, 2023). "To explore the effect of the CCL3/VIRMA/SIRT1 pathway on the ICC malignant process, we constructed subcutaneous and orthotopic tumor models in nude mice." (PMID 36691046, 2023). "In conclusion, the results of the current study confirmed that CCL3/VIRMA/SIRT1 pathway promotes ICC proliferation and tumor metastasis in vivo." (PMID 36691046, 2023). "In summary, we demonstrate that AIFM2 is frequently overexpressed in HCC and plays a crucial role in the promotion of tumor metastasis by increasing mitochondrial biogenesis and oxidative phosphorylation through activation of NAD+/SIRT1/PGC-1α signaling." (PMID 37735151, 2023). "Sirtuin 1 (SIRT1) and cullin 4B-ring E3 ligase (CRL4B) interact and cooperate as a functional unit, contributing to the epigenetic silencing of tumor suppressors, and playing an important role in regulating PCSC properties." (PMID 37173787, 2023). "The mRNA and protein expression of SIRT1 and NOX4 was significantly downregulated in the LLC tumor groups compared to the control group, as well as FOXO1 and FOXO3a in vitro." (PMID 37190306, 2023). "It is reported that the NAD+-dependent deacetylase, i.e., Sirtuin 1 (SIRT1), possesses both oncogenic and tumor-suppressive functions in PC, possibly depending on the stage of tumor progression in context-dependent manners." (PMID 37960146, 2023). "Apart from this, the upregulation of RAB8, GCF2, PCAF, G-catenin, Nrf2, HSP, SIRT1, and TWIST, etc., promotes cisplatin resistance in tumor cell." (PMID 36715825, 2023). "SIRT1 has been observed to deacetylate DNA damage repair enzymes such as WRN, APE1, XPA, and XPC and suppress tumor progression via inhibition of NF-kB." (PMID 37456463, 2023). "As an alternative approach, the levels of SIRT1 protein and its substrate Ace H3K9 were compared first in intestinal cell lines and then in human tumours." (PMID 37530744, 2023). "Further, silent information regulation factor 1 (sirtuin Type 1, SIRT1), as a kind of NAD + dependent class III histone deacetylation enzyme, involved in tumor proliferation, invasion, and metastasis." (PMID 38081857, 2023). "KLF14-mediated the suppression of IRP2 was dependent on SIRT1, which suggests a KLF14-related epigenetic mechanism in the regulation of iron homeostasis and tumor growth in HCC." (PMID 36600258, 2023). "Silent information regulation factor 1 (sirtuin Type 1, SIRT1), as a kind of NAD+ dependent class III histone deacetylation enzyme, has been found to be involved in tumor proliferation, invasion, and metastasis." (PMID 37538932, 2023). "SIRT1 is an NAD+-dependent protein deacetylase that has been shown to play a significant role in many biological pathways, such as insulin secretion, tumor formation, lipid metabolism, and neurodegeneration." (PMID 37711385, 2023). "Sirtuin 1 (SIRT1) enhances stimulation of NF‐κB pathway in macrophages and promotes TAM polarization to M1 tumor suppressor phenotype." (PMID 38098217, 2023).
tumor (continued). "βOHB increased the phosphorylation of Thr172 of AMP-activated protein kinase (AMPK), phosphorylation of Ser428 of LKB1, a tumor suppressor and a key regulator of AMPK activation, peroxisome proliferator-activated receptor-coactivator 1α (PGC1α), and Sirt1." (PMID 35513524, 2022). "SIRT1 inhibition impaired proliferation of HCC cells in-vitro and cambinol treatment resulted in an overall lower tumor burden in-vivo in an orthotopic xenograft model." (PMID 36080304, 2022). "Overexpression of SIRT1 can induce cell cycle arrest via E2F Transcription Factor 1 (E2F1) and represses CRC proliferation and tumor initiation." (PMID 35328633, 2022). "The upregulation of SIRT-1 by its activator, SRT1720, attenuates melatonin’s antioxidant and antitumor activity, indicating that its induction of ROS production in tumor cells is activated by SIRT1." (PMID 36009340, 2022). "It is also possible that 4PYR can stimulate the survival of tumor cells directly through the inhibition of the AMPD (AMP deaminase) pathway, resulting in SIRT1 stimulation." (PMID 35628582, 2022). "To ensure that galangin activates Sirt1/PGC-1α/Nrf2 signaling to attenuate skin aging in H2O2-exposed cells, we used siRNA to silence Sirt1 and PGC-1α expression; this would enable identification of the protective effects of galangin." (PMID 35163314, 2022). "Inhibition of SIRT-1 upregulates B7-H3 and TNF-α in the tumor microenvironment, thereby inducing tumor immune escape." (PMID 35906622, 2022). "EX527 is a highly selective deacetylase SIRT1 inhibitor, and KIF15-IN is a highly selective inhibitor of KIF15, both of them are considered to have a significant inhibitory effect on tumor proliferation." (PMID 36280663, 2022). "SIRT1 overexpression antagonized CK2 inhibition-mediated cellular senescence, a process thought to be an important tumor suppression process in vivo." (PMID 36009534, 2022). "However, while SIRT-1 activation is linked to tumor promoter actions under certain conditions, our findings support a context-dependent role of SIRT-1, which may be exploited to reverse tumor metabolic reprogramming." (PMID 34986886, 2022). "In non-tumor diseases, upregulated SNHG8 serves as a competitive endogenous RNA by sponging miR‐425‐5p, and inhibits the SIRT1/NF‐κB signaling pathway to attenuate the ischemia-induced microglial inflammatory response." (PMID 35659362, 2022). "It was reported that Fra-1 is a component of AP-1 complex that can promote tumor-associtated EMT by directly regulating EMT-TFs, and SIRT1 enhances the EMT process in a Fra-1-dependent manner." (PMID 35429301, 2022). "Previous studies have shown that the SIRT1/FoxO1/MDR1 pathway is hyperactivated in many tumours and mediates the multidrug resistance of tumour cells." (PMID 35022006, 2022). "The action of SIRT1 and SIRT2 is pivotal, depending on the type of tumor and the signaling pathway they affect." (PMID 35267521, 2022). "Although both SIRT1 and SIRT2 were secreted into the extracellular space, only SIRT2 deacetylated LIFR‐K620 acetylation, indicating that the tumour microenvironment of PCa has certain characteristics and functions." (PMID 35172032, 2022). "Silencing the expression of SIRT1 contributed to boosted expression of SOST, thus suppressing the growth of tumor cells." (PMID 35356205, 2022). "SIRT1, an NAD‐dependent deacetylase, contributes to tumor progression by maintaining the self‐renewal of CSCs and promoting carcinogenesis." (PMID 35674129, 2022). "We observed that NNMT promoted SIRT1 and inhibited GAP43 expression, thereby promoting tumor cell proliferation and invasion." (PMID 35884600, 2022). "Results of the meta-analysis indicated that SIRT1 was overexpressed in ESCC and the SIRT1 expression was closely related to the clinicopathological features of ESCC, such as tumor infiltration, tumor node metastasis (TNM) stage, and lymph node metastasis." (PMID 35350833, 2022).
tumor (continued). "SIRT1 is the downstream target of HIF-1α which is one of the major factors to create a hypoxic TME, contributing to tumor development and progression." (PMID 35496046, 2022). "In contrast to NASH, where SIRT1 levels are low due to the inhibitory effect of cathepsins, the levels of SIRT1 in HCC cells are high and seem to have a pro-tumor role by inducing an immunosuppressive phenotype, among others." (PMID 36289617, 2022). "In our study, treatment with UF extract and UDCA inhibited the expression of TGF-β, VEGF, N-cadherin, and SIRT-1 in FRO cells, suggesting that these agents exert suppressive effects on tumor proliferation and invasion in ATC." (PMID 34500742, 2021). "Interestingly, on the RNA level, SIRT1 negatively correlated with gene expression of a so far uncharacterized immune infiltrate, consistent with a role for functional interaction between tumor and tumor-microenvironment compartments in EwS progression (unpublished)." (PMID 33919988, 2021). "This is observed through activation of the sirtuin 1 gene/AMPK (SIRT1/AMPK) signaling pathway, known as tumor suppressor genes, and inhibition of the expression levels of MMP2 and MMP9 in NSCLC cells." (PMID 34069141, 2021). "Among the Pirh2-interacting proteins were the ones that are involved in gene expression regulation, DNA repair, apoptosis, and tumor transformation (e.g., PARP1, ku70, Sirt1, HuR, and Dicer)." (PMID 34091597, 2021). "The related studies of tumor series have shown that SNHG15 can specifically bind to miR-141 and act as endogenous RNA to regulate the expression of sirtuin 1 (SIRT1), the target gene of miR-141." (PMID 34868528, 2021). "It has been reported that miR-34a can regulate tumor angiogenesis by directly inhibiting angiogenic functions of endothelial cells by downregulating several key proteins including E2F3, SIRT1 and CDK4 in HNSCC." (PMID 33981611, 2021). "Therefore, SIRT1 may regulate the delicate balance between the suppression and promotion of tumorigenesis according to its activity level, spatiotemporal distribution, tumorigenesis stage, and tumor microenvironment." (PMID 34163012, 2021). "Conversely, some studies propose that SIRT1 and SIRT2 themselves can attend as a tumor suppressor, at least in particular circumstances." (PMID 33705642, 2021). "Glucose, hexokinase, PKM2, lactate, PDH, PDK1, SIRT1, and SIRT3, are essential glycolytic and mitochondrial metabolism enzymes controlling tumor progression or regression." (PMID 34771733, 2021). "The RT-qPCR results showed that circ-SIRT1 was highly expressed in CRC cells and tissue and was positively correlated with the depth of tumor invasion." (PMID 34660182, 2021). "The down-regulation of SIRT1 leads to tumorigenesis and up-regulation of SIRT1 inhibits the activity of several oncogenes such as HIC1 and DBC1 resulting in cell proliferation, apoptosis, and tumor suppression." (PMID 33630973, 2021). "Studies have demonstrated that SIRT1 and SIRT2 can raise the capacity of tumor cells to break through the membrane, letting tumor cells get extremely transformed and so much invasive capacity." (PMID 33705642, 2021). "All these molecules (AMPK/SIRT1/FGF21/β-klotho) and the downregulation of the STAT3/NFκB signaling pathways provide the AAV-NT mice with a physiology that hinders tumor formation." (PMID 33922238, 2021). "SIRT1 is a highly conserved mammalian NAD+-dependent histone deacetylase, acting as a key metabolic sensor that modulates EMT in tumours." (PMID 34226501, 2021). "SIRT1 and CUL4B were found to be significantly upregulated in tumors, with their level of expression positively correlated with tumor histological grades, while FOXO3 expression was negatively correlated with tumor histological grades." (PMID 34163012, 2021). "It is also known that SIRT1 and SIRT2 proteins play an important role in the tumor cells, especially during chemotherapy." (PMID 33705642, 2021).
tumor (continued). "In order to assess the possible role of each drug on brain metastasis, eight protein/gene effectors known to have a more important role in brain metastasis than in primary tumours were considered: FGFR1; Ki-67, ROBO1; S100A7; S100B; SIRT1; SLIT2; and VEGFA." (PMID 33659043, 2021). "This mitochondrial change activates SIRT1 by enhancing NAD+ levels, which inhibited glycolysis in response to energy stress and promotes tumor cell survival." (PMID 34868997, 2021). "Nuclear SIRT1, the most studied member of the SIRT family, is variably considered an oncogene or tumor suppressor gene depending on tumor context." (PMID 32340156, 2020). "The continued and post-tumour ACVR treatment replenished NAD+ levels, and continued administration also normalised the expression of Sirt1 similar to the predicted activities of its downstream targets PGC-1α/β." (PMID 32599075, 2020). "We do not know whether the decreased risk of developing an MSI tumour associated with SIRT1 rs12778366 CC and TC genotypes, as found in this study, corresponded to higher or lower levels of SIRT1 expression in colorectal cells or serum, since we did not measure SIRT1 expression." (PMID 32098999, 2020). "Together, these data suggest that TOX, and potentially TIM-3, CTLA-4, VISTA, TIGIT, KLRG1, TOX2, SIRT1, Ki-67, and Helios mRNA levels in CRC tumor tissues increase in advanced disease stages, suggesting their possible roles in CRC progression." (PMID 32393998, 2020). "SIRT1 effects are cell-dependent, allowing SIRT1 and SIRT3 to have differential effects in the cells of the tumour microenvironment." (PMID 33375613, 2020). "Contrarily, in our study, SIRT1 inhibition by NAM increased malignant cell aggressiveness, promoting tumor progression." (PMID 32340156, 2020). "Considering the sirtuins family, SIRT1 (sirtuin 1) transcript levels were higher in ESCC than in the corresponding normal mucosa, as well as in late tumour stages (III/IV) in comparison with early stages (I/II)." (PMID 32429269, 2020). "They found that the deacetylation of HINT1 by SIRT1 promotes the capacity of HINT1 to bind to transcription factors, thereby enhancing its tumor-suppressing function." (PMID 32636443, 2020). "Tumor suppressive role of miR-34a was first discovered during a study on c-Myc, LDHA, and SIRT1 oncogenes." (PMID 32440325, 2020). "DOX and T. pratense extract synergistically down‐regulated MMP‐2 and up‐regulated SIRT‐1 genes, decreased the number of CK5/6‐positive cells in tumor tissues, and inhibited metastasis of GATA‐3‐positive cells into the lung and brain." (PMID 33133558, 2020). "Compared to normal liver tissues, SIRT1 (p = 0.002), SIRT2 (p = 0.01), and SIRT4 (p = 0.045) were significantly up-regulated in tumor tissues." (PMID 33093847, 2020). "Besides, two important transcription factors that can improve T and NK cell anti-tumor effector function were over-expressed: NFκβ1, which is involved in the development, differentiation and activation of innate and adaptive immune cells, and SIRT1, a NAD+ dependent protein deacetylase." (PMID 33076479, 2020). "The expression levels of SIRT1, SIRT3, SIRT5, SIRT6, and SIRT7 were significantly correlated with tumor stage and histological grade." (PMID 32158696, 2020). "Taken together, the results of this study indicate that the tumor-suppressive function of HINT1 can be regulated by an acetylation-dependent mechanism involving CBP and SIRT1." (PMID 32636443, 2020). "In concordance with the tumor suppressor role reported for miR-199b in other tumor types, miR-199b downregulation was found to contribute to CRC progression through the modulation of the SIRT1/CREB/KISS1 pathway via SIRT1 activation." (PMID 32731550, 2020). "We believe that our findings are novel because they suggest the possibility that increased SIRT1 activity, together with treatment with an inhibitor of CHK2 that can reduce tumor pathology." (PMID 30902968, 2019).
tumor (continued). "Thus, it remains controversial whether SIRT1 acts as a tumor promoter or suppressor." (PMID 30918653, 2019). "It is reported that SIRT1 deacetylation at K14 and K20 of PH domain is necessary for binding of Akt to PIP3 and further activation during tumor angiogenesis." (PMID 32010617, 2019). "SIRT1 is a NAD-dependent class III histone deacetylase that plays major roles in regulating gene expression, DNA damage repair, metabolism, tumor development, aging, and autophagy." (PMID 30884764, 2019). "Similar to SIRT1, the impact of SIRT2 on cell viability appears to depend on the cellular context or the kind of tumor." (PMID 31817470, 2019). "SIRT1 restraints the progression of GC via the modulation of ARHGAP5 expression, representing a novel mechanism of SIRT1 as a tumor suppressor." (PMID 31130822, 2019). "Thus, SRT2183 might exert a tumor or cell-specific effects on the activation of Sirt1 substrates." (PMID 31319814, 2019). "For example, one study showed that butyrate suppresses tumor growth and induces apoptosis by regulation of expression of HDAC, SIRT-1, caspase 3, and NFκB." (PMID 30937307, 2019). "Inhibiting SIRT1 in LCSCs reduced SOX2 expression and strongly repressed tumor growth in both in vivo and in vitro models." (PMID 31608282, 2019). "Over the past decade, SIRT1 has been studied for its important role in tumorigenesis, as it is overexpressed in tumor tissue and tumor cells, such as human AML, and SIRT1 is thought to function as a tumor-promoting factor." (PMID 31850196, 2019). "Eight miRNA-449-family target genes (CDC25A, SIRT1, GMNN, E2F1, E2F3, BCL2, CDK2, and CCNE2) were selected; all of them involved in tumor development, cell cycle, and apoptosis." (PMID 30926829, 2019). "Multiple tumor-suppressive microRNAs (miRNAs) are downregulated in HCC and, as a consequence, permit SIRT1-induced tumorigenicity." (PMID 31608282, 2019). "Upon stress, SIRT1 can be relocate to DNA damaged sites, favoring abnormal epigenetic marks and culminating in the expression of transcriptionally repressed DNA loci, such as aging- and tumor-related genes, which might favor the development and progression of tumors." (PMID 31261609, 2019). "By deacetylating SMAD4, SIRT1 represses the effect of TGF-β signaling on MMP7 (a SMAD4 target gene) and consequently cell migration and tumor metastasis in breast cancer and oral squamous cell carcinoma." (PMID 30250020, 2018). "We suggested that SIRT1 most probably has an oncogenic role in HRBC subtypes and a tumor-suppressor role in TNBC subtype." (PMID 30093977, 2018). "Interestingly, some studies claimed that SIRT1 could inhibit tumor progression." (PMID 29752439, 2018). "On the other hand, SIRT1 is also reported to mediate BRCA1 signaling and inhibit tumor growth through downregulation of oncogenes or by repressing the activity of oncoproteins such as β-catenin and survivin." (PMID 29340027, 2017). "In fact, protein-protein interaction between SIRT1 and DNMT3B was observed both in 4C pre-malignant melanocytes and in 4C11- and 4C11+ tumor cells." (PMID 29383100, 2017). "SIRT1 has been shown to interact with and activate TIAM1 (T-cell lymphoma invasion and metastasis 1) and Rac1 in tumor cells, in parallel with TIAM1 acetylation." (PMID 29074993, 2017). "Further, the levels of c-Myc, SIRT1 and PGC-1α protein were reduced in the tumor samples from mice treated with cryptolepine as compared with the tumor samples from vehicle-treated control mice." (PMID 28473727, 2017). "miR-449a has been reported to suppress tumor cell proliferation/growth and survival by targeting CDK6, CDC25A, Sirt1, HDAC1, cyclinD1, WISP2, and c-Met." (PMID 29254139, 2017). "Overexpression of SIRT1 decreased AKT (PKB) level and further inhibited phosphorylation of DLC1 in spontaneous neoplasms by resveratrol." (PMID 28903430, 2017).